PIGO (phosphatidylinositol glycan anchor biosynthesis class O)
Description:
Catalytic subunit of the ethanolamine phosphate transferase 3 complex that transfers an ethanolamine phosphate (EtNP) from a phosphatidylethanolamine (PE) to the 6-OH position of the third alpha-1,2-linked mannose of the a 2-acyl-6-[alpha-D-mannosyl-(1->2)-alpha-D-mannosyl-(1->6)-2-phosphoethanolamine-alpha-D-mannosyl-(1->4)-alpha-D-glucosaminyl]-1-(1-radyl,2-acyl-sn-glycero-3-phospho)-1D-myo-inositol (also termed H6) intermediate to generate a a 2-acyl-6-[6-phosphoethanolamine-alpha-D-mannosyl-(1->2)-alpha-D-mannosyl-(1->6)-2-phosphoethanolamine-alpha-D-mannosyl-(1->4)-alpha-D-glucosaminyl]-1-(1-radyl,2-acyl-sn-glycero-3-phospho)-1D-myo-inositol (also termed H7) and participates in the tenth step of the glycosylphosphatidylinositol-anchor biosynthesis.
Synonyms: PIG-O; hGPCR43; DKFZp434M222; FLJ00135; HPMRS2
Tractability: Antibody: UniProt predicts a signal peptide or a membrane-spanning region. PROTAC: ubiquitination databases record sites on it; its protein half-life has been measured.
Target class: Enzyme; Transferase
Gene: Protein-coding gene on chromosome 9 (35,085,493 to 35,096,632, reverse strand). Ensembl gene ENSG00000165282.
Subcellular location: Endoplasmic reticulum membrane
Subcellular location (Human Protein Atlas): Nucleoli; Nucleoplasm
Pathways (Reactome):
Metabolism of proteins: Synthesis of glycosylphosphatidylinositol (GPI)
Gene Ontology:
Molecular function: mannose-ethanolamine phosphotransferase activity; transferase activity, transferring phosphorus-containing groups
Biological process: GPI anchor biosynthetic process
Cellular component: membrane; endoplasmic reticulum membrane
Genetic constraint (gnomAD): Loss-of-function variants: 66 observed, 90.99 expected, observed/expected ratio (o/e) 0.73, 90% interval 0.59 to 0.89. The upper end of that interval is the gene's LOEUF score, 0.89, which puts it in group 3 of 6, group 1 being the genes least tolerant of losing a copy. Missense variants: 1,202 observed, 1,419.3 expected, observed/expected ratio (o/e) 0.85, 90% interval 0.81 to 0.89. Synonymous variants: 570 observed, 586.45 expected, observed/expected ratio (o/e) 0.97, 90% interval 0.91 to 1.04.
Gene-disease validity (ClinGen):
ClinGen rates the evidence that PIGO causes each of these diseases.
complex neurodevelopmental disorder (autosomal recessive): Definitive. A disorder that involves more than one phenotype associated with the central nervous system, including but not limited to intellectual disability, autism, and seizures (epilepsy).
Homologues: Orthologues: chimpanzee PIGO (99% identical), macaque PIGO (92% identical), dog PIGO (89% identical), guinea pig PIGO (89% identical), rabbit PIGO (88% identical), pig PIGO (87% identical), rat Pigo (87% identical), mouse Pigo (86% identical), tropical clawed frog pigo (52% identical), zebrafish pigo (44% identical), Drosophila melanogaster PIG-O (30% identical), Caenorhabditis elegans pigo-1 (26% identical).
Diseases named in the same sentence as PIGO in open-access papers:
PIGO is named in the same sentence as 24 diseases in open-access papers, as found by Europe PMC text mining. Sharing a sentence is not in itself a finding about the gene and the disease. The quoted sentences say what the papers report.
hyperphosphatasia (10 papers, 2017 to 2025). "Hyperphosphatasia with impaired intellectual development syndrome-2 (OMIM: #614749) is an autosomal recessive genetic disorder caused by pathogenic variants in the PIGO gene." (PMID 41169893, 2025). "PIGO mutations are also related to hyperphosphatasia with mental retardation syndrome, which is also known as “Mabry Syndrome”." (PMID 39767685, 2024). "As hyperphosphatasia in IGD with PIGO deficiency is caused by secretion of the processed precursor protein of ALP without GPI anchoring, its reproduction in these Pigob/b and Pigob/− mice indicated that GPI biosynthesis was impaired." (PMID 35661110, 2022). "Recently, many individuals with IGD possessing PIGO mutations have been reported, and they show a wide range of symptoms, such as hyperphosphatasia, intellectual disability, developmental delay, epilepsy, and organ anomalies." (PMID 35661110, 2022). "PIGV and PIGO variants are associated with reduced GPI-AP surface levels and increased extracellular secretion into the extracellular space, resulting in hyperphosphatasia." (PMID 38790248, 2024). "Mutations in six different genes (PIGV, PIGY, PIGO, PGAP2, PIGW, and PGAP3) involved in GPI-anchor biosynthesis have been shown to cause hyperphosphatasia with mental retardation syndrome (HPMRS)." (PMID 29119105, 2017). "Recently, mutations have been identified in six genes (PIGA, PIGY, PIGO, PGAP2, PIGW and PGAP3) encoding proteins in the Glycosyl phosphatidylinositol(GPI)-anchor-synthesis pathway in individuals with hyperphosphatasia with impaired intellectual development syndrome(HPMRS)." (PMID 39687712, 2024). "To date, mutations in six genes (PIGV, PIGY, PIGO, PGAP2, PIGW, and PGAP3) have been shown to cause hyperphosphatasia with mental retardation syndrome (HPMRS) in an autosomal recessive mode of inheritance (no autosomal dominant mutations have been reported thus far)." (PMID 29119105, 2017).
Mabry syndrome (6 papers, 2013 to 2024). "In a real data set with exomes of four family members, two sisters affected by Mabry syndrome and their healthy parents, the disease-causing gene PIGO, which harbors the pathogenic compound heterozygous variants, could be readily identified." (PMID 23940540, 2013). "Hyperphosphatasia Mental Retardation syndrome (HPMRS, MIM 239300, MIM 214749, and MIM 614207), also known as Mabry syndrome, was found to be associated with PIGV (MIM 610274), PIGO (MIM 614730),PGAP2 (MIM 615187) and PGAP3 (MIM 611801) mutations." (PMID 25885527, 2015).
epilepsy (4 papers, 2017 to 2024). A brain disorder characterized by episodes of abnormally increased neuronal discharge resulting in transient episodes of sensory or motor neurological dysfunction, or psychic dysfunction. "We report a case of a male term newborn with two compound heterozygous variants of the PIGO genes, presenting with encephalopathy, drug-resistant epilepsy, and gastrointestinal abnormalities." (PMID 39767685, 2024).
Epileptic encephalopathy (2 papers, 2024 to 2025). A condition in which epileptiform abnormalities are believed to contribute to the progressive disturbance in cerebral function. "The analysis in the context of epileptic encephalopathies identified two compound heterozygous variants (c.839T>C; c.2285C>T) in the PIGO gene, which were associated with hyperphosphatasia syndrome and intellectual disability type 2 (OMIM 614749)." (PMID 39767685, 2024). "Regarding the PIGO gene, several case reports have described mutations associated with epileptic encephalopathy both with and without an increase in blood alkaline phosphatase levels." (PMID 39767685, 2024).
hyperphosphatemia (2 papers, 2020 to 2025). Abnormally high level of phosphate in the blood. "Hyperphosphatemia is a characteristic symptom of some GPI deficiencies, including PIGO, PIGW, PGAP2, etc.." (PMID 32220244, 2020).
deficiencies (1 paper, 2020). "Pyridoxine treatment was reported to be effective for seizures in some patients with inherited GPI deficiencies, such as PIGV or PIGO mutations." (PMID 32220244, 2020).
megacolon (1 paper, 2018). "To date, megacolon has only been found to be associated with PIGV, PIGO, and PGAP2 mutations." (PMID 29310717, 2018).
prostate tumours (1 paper, 2023). "However, PIGO, which encodes phosphatidylinositol glycan anchor biosynthesis class O protein, has been reported to be upregulated in prostate tumours, suggesting its role in promoting cell growth." (PMID 37924098, 2023).
infection (1 paper, 2025). The state of being infected such as from the introduction of a foreign agent such as serum, vaccine, antigenic substance or organism. "Among the genes with the greatest positive effect on infection efficiency after knockout were multiple GPI biosynthesis genes: GPAA1, PIGA, PIGV, and DPM1 knockouts increased infection over 8-fold compared to control, while PIGO knockout increased infection approximately 4-fold." (PMID 40901862, 2025).
PIGO also shares sentences with these, for which no sentence is quoted: developmental delay (3 papers); Hirschsprung disease (3); Intellectual disability (3); genetic diseases (2); Ataxia (1); brain injury (1); colon cancer (1); congenital disorder of glycosylation (1); Encephalopathy (1); intestinal disorder (1); metabolic disorder (1); movement disorder (1); neurological disorder (1); Palmoplantar keratoderma (1); tumour (1).